Y_RNA (Y RNA )
Gene: Miscellaneous RNA gene on chromosome 15 (56,634,038 to 56,634,167, reverse strand). Ensembl gene ENSG00000276696.
Homologues: Orthologues: chimpanzee Y_RNA (100% identical), pig Y_RNA (51% identical). Paralogues in human: Y_RNA (65% identical), RNY3P4 (63% identical), Y_RNA (62% identical), Y_RNA (61% identical), Y_RNA (60% identical), RNY3 (59% identical), Y_RNA (59% identical), RNY3P1 (58% identical), RNY3P16 (58% identical), Y_RNA (58% identical), RNY3P8 (57% identical), Y_RNA (57% identical), and 80 more.